GABPB1 (GA binding protein transcription factor subunit beta 1)
Diseases named in the same sentence as GABPB1 in open-access papers (continued):
Sharing a sentence is not in itself a finding about the gene and the disease.
tumor (14 papers, 2020 to 2025). "Notably, in adenocarcinoma patients, the expression of GABPB1 was also significantly associated with molecular subtypes and tumor pathway activation, such as apoptosis, the cell cycle and EMT." (PMID 38466508, 2024). "Our clinical analysis was indicative that the loss of GABPB1 gene expression could potentially contribute to tumor progression, highlighting the need for further understanding of the regulatory mechanism underlying its gene expression." (PMID 35326537, 2022). "Accordingly, inhibiting TERT or its upstream tumor-specific transcription factor GA-binding protein transcription factor subunit beta 1 (GABPB1) was shown to inhibit tumor growth." (PMID 40463649, 2025). "In NSCLC, the expression of GABPB1 was correlated with the infiltration of various tumor immune cells." (PMID 38466508, 2024). "The results showed that GABPB1 was overexpressed in human NSCLC tumor tissue and cell lines and that downregulation of GABPB1 inhibited cell proliferation and promoted cell apoptosis in vitro." (PMID 38466508, 2024). "We analysed tumor data from public databases to assess the expression of GABPB1 in NSCLC and its correlation with patient prognosis and investigated GABPB1 expression and methylation patterns in relation to the tumor microenvironment." (PMID 38466508, 2024). "Analysis of the extensive TCGA and GTEx datasets through the use of GEPIA2 and GSCA revealed that GABPB1 was differentially expressed in tumor tissue compared with normal tissue across the majority of tumor species." (PMID 38466508, 2024). "The correlation with immune infiltrating cells exhibiting different immunoregulatory effects showed the opposite direction, with attenuation of the tumor immunosuppressive effect exhibited by GABPB1." (PMID 38466508, 2024). "Intriguingly, the presence of TERT promoter mutations represents a featured hallmark for aggressive TCs whereas GABPA and GABPB1 expression is downregulated in those tumours." (PMID 36394204, 2022). "Several lines of evidence suggest that GABPA and GABPB1 serve as tumour suppressors to inhibit TC aggressiveness." (PMID 36394204, 2022). "Likely, GABPB1 has a tumor-suppressive function in the TC pathogenesis to counteract the development of aggressive diseases." (PMID 35326537, 2022). "Furthermore, the combination treatments (EGFR and TERT or EGFR and GABPB1) led to even greater tumor growth inhibition than the single treatments." (PMID 40463649, 2025). "The expression and methylation of GABPB1 affect the tumor microenvironment." (PMID 38466508, 2024). "The differential expression of GABPB1 was associated with clinical features and patient prognosis, and the impact of GABPB1 methylation on the tumor immune microenvironment may be a breakthrough point in this research." (PMID 38466508, 2024). "Reported studies have demonstrated that GABPB1 may have carcinogenic or anticancer roles in different tumor contexts and has the potential for use as a therapeutic target in glioblastoma and bladder cancer." (PMID 38081871, 2023). "After confirmation of the utility of HP [1-13C]6PG for assessing TERT expression in live cells, our next step was to assess whether we could observe changes in TERT expression after TERT or GABPB1 targeting in preclinical in vivo tumor models." (PMID 36997627, 2023). "The aberrant DNA methylation is a common mechanism to silence tumor suppressor genes, and here we observed that hypermethylation of GABPB1 promoter is prognostic for shorter disease-free survival besides an inhibitory effect of GABPB1 on TC cell invasion." (PMID 35326537, 2022). "The underlying mechanism in which GABPB1 is involved in suppressing tumor progression remains elusive and seems to be independent of BRAFV600E mutation." (PMID 35326537, 2022).
tumor (continued). "Therefore, we hypothesize that high level of HOMER3 in NSCLC may activate the expressions of downstream mitochondrial genes by GABPB1, thereby promoting mitochondrial anabolism, and creating the conditions for tumor proliferation and metastasis." (PMID 38081871, 2023). "When TERT or GABPB1 were inhibited simultaneously with EGFR, the combination treatment resulted in enhanced inhibition of cell and tumor growth as well as animal survival compared not only to controls but also to any of the single treatments." (PMID 40463649, 2025). "Scientists have studied the lncRNA GABPB1 intronic transcript in NSCLC and found that the expression of the GABPB1 intronic transcript was significantly downregulated in tumor samples from NSCLC patients and correlated negatively with tumor stage." (PMID 38466508, 2024). "Our research verified that GABPB1 promotes the tumorigenesis of NSCLC and has an inhibitory effect on tumor immunity." (PMID 38466508, 2024). "We found that besides the reported oncogenic role of GABPB1 in activating TERT, it also has tumor-suppressive functions in TC." (PMID 35326537, 2022). "Gene group 2 displayed a significant upregulation of E2F transcription activators (E2F1, E2F2, E2F3, and E2F6) and tumor-specific transcription factors (MYCN, RUNX1, and GABPB1) in advanced Rb." (PMID 35626705, 2022). "We also measured the mRNA expression of the GABP TF complex subunits, GABPB1 and GABPA, which shows detectable and robust expression in all available tumor regions." (PMID 36114166, 2022). "Our results suggest that GABPB1 is required for TERT expression and telomerase activation, but itself serves as a tumor suppressor to inhibit TC progression." (PMID 35326537, 2022). "Studies have indicated that the lncRNAs, MIAT, GABPB1, and PDPK2P influence tumor progression in HCC." (PMID 34876904, 2021). "Because GABPB1 is a subunit of GABP, which binds to the mutant TERT promoter without interfering with the normal TERT promoter, GABPB1 is viewed as a tumor-specific therapeutic approach with potentially limited toxicity." (PMID 36997627, 2023). "Furthermore, we report on the elevation of tumor-specific transcription factors such as RUNX1 and GABPB1, and the reduced expression of FOXO3 that is low in the advanced group." (PMID 35626705, 2022). "Moreover, the present study highlighted that the tumor-suppressive functions of GABPB1 may be independent of the TERT promoter since we found a similar enhanced invasive ability after inhibition of GABPB1 in TC cells regardless of their TERT promoter mutation status." (PMID 35326537, 2022). "Notably, four of these TFs—RUNX3, GABPB1, GABPA, and BCL6B—are known tumor suppressors." (PMID 40432923, 2025).
GABPB1 also shares sentences with these, for which no sentence is quoted: bladder cancer (2 papers); adenocarcinoma (1); astrocytoma (1); colon cancer (1); cutaneous melanoma (1); diabetic nephropathy (1); end-stage renal disease (1); hemochromatosis (1); Huntington disease (1); liver steatosis (1); neuroblastoma (1); oligodendroglioma (1); ovarian carcinoma (1); Pan (1); renal cell carcinoma (1); sarcopenia (1).